TGFB2 (transforming growth factor beta 2)
Diseases named in the same sentence as TGFB2 in open-access papers (continued):
Sharing a sentence is not in itself a finding about the gene and the disease.
glaucoma (continued). "In patients with glaucoma, increased levels of transforming growth factor-β2 (TGFβ2) in the aqueous humor (AH) have been also observed in numerous studies by different laboratories, which are believed to contribute to the increased ECM deposition and stiffness." (PMID 31695131, 2019). "Human TM cells treated with TGFβ2 also increase the level of plasminogen activator inhibitor (PAI), fibronectin, collagen and the promatrix metalloproteinase‐2.40, 41, 48, 49 In summary, TGF‐βs, especially TGF‐β2, play an important role in pathogenesis of glaucoma." (PMID 30659738, 2019). "Both TGFβ2-targeting and TGFβ1-specific ASONs showed a reduction in post-operative scarring after a single administration at the time of surgery in two different animal models of human glaucoma filtration surgery." (PMID 29615587, 2016). "TGFβ2 is elevated in the anterior segment of glaucoma patients, and while the mechanism(s) responsible for elevated expression is unknown, substantial evidence implicates TGFβ2 as a contributing factor in ocular hypertension." (PMID 22876128, 2012). "In addition, decreased levels of pyruvate kinase, L-lactate dehydrogenase A chain, ubiquitin-60S ribosomal protein L40, transforming growth factor beta-2, aldehyde dehydrogenase, and pleiotrophin suggest a weakened ability of glaucoma patients to adapt to oxidative stress." (PMID 40243897, 2025). "Here, we followed up on these studies and further investigated the role of autophagy in glaucoma in autophagy-deficient DBA/2J-Atg4bko mice, which we generated in our laboratory, and in Atg4bko mice subjected to the transforming growth factor beta 2 (TGFβ2) chronic ocular hypertensive model." (PMID 37620383, 2023). "It is known that increased TGFβ2 levels in glaucoma may be due to epigenetics, suggesting that it is the increased TGFβ signaling that occurs first leading to production of excess ECM and DAMPs, which would then activate TLR4 leading to a feedforward signaling loop." (PMID 35912101, 2022). "In addition to TGFB2, many of the genes that were altered belonged to classes of proteins such as ECM proteins, cell adhesion molecules and transcription factors, that are known to be altered in glaucoma and either regulate TGFβ2 signaling or are regulated by TGFβ2 signaling." (PMID 34440692, 2021). "It is noteworthy that several other genes that were upregulated by αvβ3 integrin signaling are associated with various types of glaucoma and IOP regulation further supporting the idea that αvβ3 integrin and the concomitant increase in TGFB2 expression together may be playing a role in glaucoma." (PMID 34440692, 2021). "In addition, we also explored whether CTSK is regulated by dexamethasone (DEX), TGFβ2, Endothelin 1 (Endo-1), and connective tissue growth factor (CTGF); each of which has been implicated in elevated IOP and glaucoma." (PMID 34831087, 2021). "Interestingly in glaucoma patients, the expression of TGFβ2 is abnormally higher than that from normal people, suggesting TGFβ signalling may play an important role in the progression of glaucoma." (PMID 30659738, 2019). "Therefore, studying cytokine expression could provide insight into the pathology of glaucoma as pertaining to TGFβ2." (PMID 27924833, 2016). "All together, these results not only support the involvement of TGFβ2 in fibrotic HTM, as seen in several types of glaucomas, but also suggest the role of TGFβ2 in tissue hardening that may take place as a result of crosslinked, dense arrangements of collagen IV, fibronectin and laminin." (PMID 27924833, 2016). "Together, these data demonstrate that levels of active TGFβ2 as well as YAP and TAZ nuclear localization and transcriptional activity are elevated in GTM cells isolated from patients with glaucoma compared to normal HTM cells." (PMID 35300422, 2022). "The function of TGFβ2 and CTGF in the retina, specifically in the experimental glaucoma animal model, is not yet fully understood." (PMID 35456925, 2022).
glaucoma (continued). "Transforming growth factor-β2 (TGFβ2) and secreted frizzled-related protein-1 (SFRP1) levels were detected in aqueous humor levels (AH) samples from different glaucoma patients." (PMID 33578928, 2021). "The findings presented herein indicate that DEX or TGFβ2 resulted in mild and severe down-sized and stiff 3D HTM spheroids, respectively, thus making them viable in vitro HTM models for steroid-induced and primary open angle glaucoma." (PMID 34588570, 2021). "The essential role of these developmental glaucoma genes for the development of the anterior segment and in the development of TM implies that FOXC1, TGFβ2, and BMP4 are crucial for the normal development of drainage structures and preservation of normal IOP." (PMID 22736943, 2012). "Recent studys have found that transforming growth factor-beta 2 (TGF-β2), known to regulate the ECM metabolism including fibronectin, collagen, and elastin, is elevated in the aqueous humor and TM of the glaucoma patient." (PMID 22876112, 2012). "This suggests that TM cells in vivo are unlikely to upregulate TGFβ2 mRNA expression during glucocorticoid-induced glaucoma unless the cells have been induced to re-enter the cell cycle." (PMID 36766846, 2023). "TGFβ2-induced fibrogenesis with subsequent ECM deposition and stiffness are believed to be the culprit of decreased resistance to AH outflow and IOP elevation in primary open angle glaucoma." (PMID 37620383, 2023). "One predominant hypothesis indicates TGFβ2-induced ECM synthesis as a major player in instigating and exacerbating the increased ECM buildup and dysregulation in glaucoma." (PMID 37686046, 2023). "Examples of these include genetic models of glaucoma (MyocY437H mice), OHT induced by transduction of the TM with glaucoma-related genes (e.g., MYOC, TGFβ2, GREM1, CTGF, DKK1, SFRP1, CD44, Cre and inducible transgene models, genome editing), as well as glucocorticoid-induced OHT models." (PMID 35129590, 2022). "Primary human normal and glaucoma LC cells were grown to confluency and treated with or without TGFβ2 for 24 h." (PMID 34201109, 2021). "We detected TGFβ2 and SFRP1 in AH samples of the control and different glaucoma patients." (PMID 31382918, 2019). "TGFβ2 and SFRP1 may play different roles in the pathogenesis and pathophysiology of different types of glaucoma." (PMID 31382918, 2019). "In some of the JIAU patients, high TGFβ-2 levels could be produced to control SAA, but this process might promote the development of glaucoma." (PMID 29675026, 2018). "Although the exact etiology of glaucoma remains unknown, a number of studies have now determined that elevated levels of transforming growth factor β2 (TGFβ2) and connective tissue growth factor (CTGF) and the use of glucocorticoids can lead to the development of glaucoma." (PMID 34440692, 2021). "Increased deposition of fibronectin fibrils containing EDA+fibronectin by TGFβ2 is thought to be involved in the reduction of aqueous humor outflow across the trabecular meshwork (TM) of the eye and the elevation in intraocular pressure (IOP) observed in primary open angle glaucoma (POAG)." (PMID 32822410, 2020). "Despite extensive studies on their effects on the HTM, it is not clear whether ROCK inhibitors can correct TGFβ2-induced fibrotic ECM build-up and myocilin over-expression, which have been linked to glaucoma." (PMID 27924833, 2016). "In vitro studies have shown that TGFβ2 and BMP4 act in concert to maintain a balance between ECM deposition and degradation, and may play an important role in glaucoma pathogenesis through mis-regulation of ECM synthesis and cross-linkage of ECM components of the TM." (PMID 22736943, 2012). "In the AACG group, we did not observe significant differences in AH levels of TGFβ2 and SFRP1 between patients treated with anti-glaucoma medications and those who were not treated." (PMID 31382918, 2019).
glaucoma (continued). "This represents the first association analysis of TGFβ2, BMP4, and FOXC1; the lack of association of common polymorphism does not provide evidence in support of the hypothesis that these genes play a significant genetic role in the pathogenesis of glaucoma among white British subjects." (PMID 22736943, 2012). "In order to analyze whether anti-glaucoma medications affected the experimental results, we divided AACG patients with high IOP into “drugs” group and “no drug” group, and found that there was not significantly difference in concentrations of bioactive TGFβ2 and SFRP1 between these two groups." (PMID 31382918, 2019).
glioma (99 papers, 2000 to 2026). A benign or malignant brain and spinal cord tumor that arises from glial cells (astrocytes, oligodendrocytes, ependymal cells). "Recent studies have shown that TGFB2 expression is upregulated in gastric cancer, non–small cell lung cancer, gallbladder cancer, colorectal carcinoma, and high-grade glioma, which is associated with poor prognosis." (PMID 36105107, 2022). "Taken together, in the present study, we established an IRRS prognostic model, composed of VEGFA, SOCS3, SPP1, and TGFB2 core DE IRGs, for risk stratification and survival prediction for glioma patients." (PMID 34497663, 2021). "Trabedersen is directed against TGF-β2 (transforming growth factor beta 2), which is overexpressed in cancer in particular in glioma and is associated with tumor progression." (PMID 32373584, 2020). "Interestingly, TGFβ2 is also associated with an increment in glycolysis in glioma and it is released also by several immune cells of the TME as TAMs, particularly those with an M2 profile, and cancer-associated fibroblasts (CAFs)." (PMID 38139462, 2023). "TCF7, THY1, and TGFβ2 are all associated with glioma stemness, leading to immunosuppression." (PMID 35599254, 2022). "In our present study, four progression-related DE IRG (including VEGFA, SOCS3, SPP1, and TGFB2 genes)constituting a signature can perform risk stratification for glioma patients and disclosed that patients with high risk seemed to have an approximate 14.3%-29.8% 5-year survival rate." (PMID 34497663, 2021). "Therefore, the present study investigated the mechanism underlying the induction of proliferation by TGFβ2/Smads in glioma." (PMID 25891822, 2015). "We identified seven cytokines from previous glioma or allergy literature (IL4, IL13, IL5, IL6, IL10, IFNG and TGFB2) to determine whether, they were associated with glioma before diagnosis." (PMID 26352148, 2015). "It has also been extensively studied in gliomas, yet the specific interactions between TGFβ1, TGFβ2, and TGFβ3 isoforms in astrocytic tumors remain poorly understood." (PMID 40620718, 2025). "TREM1 is preferentially expressed by M2-like TAMs and induces a mesenchymal-like state in glioma stem cells (GSCs) by modulating the secretion of TGFβ2, thereby activating the TGFβR/SMAD2/3 signaling pathway in GSCs." (PMID 41394801, 2025). "TGFB2 is a critical regulator of glioma cell migration and is likely one of the significant mechanisms underlying glioma metastasis." (PMID 39660139, 2024). "For instance, ITD‐1, a drug that suppresses TGFβ2, prevents Smad2/3 phosphorylation, thereby inhibiting glioma cell and gastric cancer cell invasion." (PMID 38531630, 2024). "TGFB1 and TGFB2 have been identified as the most highly expressed tumor-promoting cytokine in the TME of gliomas, prompting us to characterize the abundance of TGFB1 and TGFB2 mRNA addition to the upregulation of TAM cell surface markers." (PMID 38539537, 2024). "We observed that significant upregulation of mRNA expression levels for three TAM markers, MSR1/CD204, CD86, and CD68, suggested that TGFB2 is pivotal in establishing a pro-tumorigenic TME in gliomas mediated through TAMs." (PMID 38539537, 2024). "Our present study supports targeting the TGFB2 mRNA through inhibition or RNA interference as a potential therapeutic strategy to promote an anti-glioma immune response." (PMID 38539537, 2024). "It has been demonstrated that lactate induces migration and cellular invasion in high-grade glioma which overexpresses higher LDHA levels through transforming growth factor β2 (TGFβ2)/integrin αvβ3/MMP2 signaling." (PMID 38139462, 2023). "Our study fills a significant gap in our understanding of the clinical significance of high TGFB2 expression in pediatric high-grade gliomas." (PMID 36980562, 2023).
glioma (continued). "Enriched TGFB2 expression levels are usually observed in the later stages of tumor progression and in up to 95% of high-grade gliomas, which initiates an autocrine loop to promote its own expression and enable oncogenic activity." (PMID 35646656, 2022). "An analysis of the differentiation of the normalized values of fluorescent signals showed that the expression levels of TGFβ1 and TGFβ2 were statistically significantly changed in gliomas of different stages." (PMID 35454784, 2022). "Some studies have reported that the TGFβ2 signaling pathway plays a pro-cancer role in a variety of tumors, such as highly aggressive gliomas, breast cancers, and squamous cell carcinomas." (PMID 35620459, 2022). "TGFB2, a member of the transforming growth factor-β family, is specifically overexpressed in highly aggressive glioma and is involved in brain tumor development." (PMID 35646656, 2022). "Lactate has also been shown to activate transforming growth factor-β2 (TGFβ2), which then increases glioma cell migration." (PMID 34831316, 2021). "Pro‐inflammatory factors have been described in glioma, and it is generally considered that IL‐6, IL‐8, CXCL1, CXCL10 and TGFβ2 are pro‐tumour cytokines closely related to glioma progression." (PMID 34216174, 2021). "In gliomas, TAGLN2 is a potential oncogenic factor, which is regulated by TGFβ2 to promote glioma invasion and growth." (PMID 34093830, 2021). "Transforming growth factor-beta 2 (TGF-β2)-induced autophagy is also essential for glioma invasion because it affects epithelial-mesenchymal transformation and metabolism conversion, with particular effects on mitochondria trafficking and membrane potential." (PMID 34204169, 2021). "In glioma cells, lactate induces the expression of transforming growth factor-β2 (TGFβ2), a key regulator of glioma cell migration." (PMID 33153193, 2020). "TGFB2 signaling is relevant to pathogenesis of many cancers, including gliomas and pancreatic cancers (Dietrich, Dutoit, Tran Thang, & Walker, 2010; Hau, Jachimczak, Schlaier, & Bogdahn, 2011)." (PMID 30680959, 2019). "Glioma-associated DEGs AKT2, CCL3, STAT2, VEGFC were up-regulated and HIF1A, KRAS, RET, TGFB2 were down-regulated specifically in the dogs." (PMID 29352201, 2018). "The TGFβ type I receptor specific inhibitor SB431542 prevented TAGLN2 induction, and therefore further supported a role for TGFβ2/Smad signaling in the regulation of TAGLN2 in glioma." (PMID 29110682, 2017). "Furthermore, systemic administration of the antisense oligonucleotide targeting TGFB2 in glioma-bearing mice led to prolonged survival and increased immune cell infiltration within tumors." (PMID 40338274, 2025). "TGFB2 can be directly targeted using TGFB2-specific synthetic phosphorothioate antisense oligodeoxynucleotide (OT-101), which reached completion in phase 2 clinical trials in gliomas and pancreatic cancer." (PMID 38539537, 2024). "Third, glioma cells have permanent expression of the immunosuppressive molecules TGFβ1 and TGFβ2." (PMID 38168422, 2023). "In addition, DKK3 interacts with immune system-related proteins, including TCF7, THY1, and TGFβ2, and induces proliferation, angiogenesis, invasiveness, and immunosuppression of glioma cells." (PMID 35599254, 2022). "Three immune genes related to glioma prognosis were identified as TGFB2, VIM, and TNFRSF12A." (PMID 33937046, 2021). "IL‐6, CXCL1 and TGFβ2 play an important role in glioma radiotherapy resistance." (PMID 34216174, 2021). "In gliomas, the expression levels of TGFB2 are used to evaluate stages of tumor progression." (PMID 34136553, 2021). "Transforming growth factor-beta 2 (TGF-β2) is a secreted protein known as an immunosuppressive molecule, whose dysregulated signaling contributes to the initiation and progression of many cancers, including glioma." (PMID 33228738, 2020).